REN (renin)
Diseases named in the same sentence as REN in open-access papers (continued):
Sharing a sentence is not in itself a finding about the gene and the disease.
Hypertension (continued). "Activation of the renin-angiotensin system (RAS), elevated oxidative stress and inflammation, and sympathetic hyperactivity in the cardiovascular organs and cardiovascular regulatory systems, are all involved in the pathogenesis of hypertension." (PMID 40356772, 2025). "From the perspective of pathophysiological mechanism, hypertension activates the renin-angiotensin-aldosterone system (RAAS), resulting in aggravation of vasoconstriction and water and sodium retention, further elevating hypertension and affecting microcirculation." (PMID 41409236, 2025). "Renin-angiotensin-aldosterone system inhibitors (RAASi) are primarily used for the treatment of hypertension and diabetic/non-diabetic reno-cardiovascular diseases." (PMID 40747151, 2025). "Renin-angiotensin system (RAS) inhibitors, particularly angiotensin receptor blockers (ARBs) and angiotensin-converting enzyme inhibitors (ACEIs), play a crucial role in hypertension management." (PMID 40255834, 2025). "PRO20 can effectively inhibit PRR by specifically blocking theinteraction between renin/prorenin and PRR, with emerging evidence that it couldpotentially attenuate hypertension." (PMID 40351692, 2025). "Additionally, vitamin D has been found to reduce the activity of the renin-angiotensin-aldosterone system (RAAS), leading to vasodilation and a potential protective effect against hypertension." (PMID 40773469, 2025). "Concurrently, the renin–angiotensin–aldosterone system (RAAS) exacerbates these maladaptive responses, further promoting renal damage and systemic vascular resistance, thus establishing a vicious cycle of renal deterioration and worsening hypertension." (PMID 40868205, 2025). "Similarly, renin-angiotensin system blockers (ACE inhibitors or ARBs), as first-choice treatments for diabetes with hypertension, have been shown to significantly improve prognosis." (PMID 41255513, 2025). "Additionally, dipeptides that include valine or alanine have been shown to inhibit enzymes such as ACE, renin, and DPP IV, indicating their possible roles in managing hypertension and diabetes." (PMID 41585459, 2025). "Renin, a key aspartic protease central to the renin–angiotensin–aldosterone system (RAAS), remains a therapeutic target for hypertension despite the withdrawal of the only approved direct renin inhibitor, Aliskiren, due to unfavorable drug–drug interactions and safety concerns." (PMID 41373556, 2025). "This condition leads to several significant pathophysiological changes, including the activation of the renin–angiotensin–aldosterone system (RAAS) and the overproduction of aldosterone, which largely contribute to the development of arterial hypertension and its consequences." (PMID 39859256, 2025). "The renin–angiotensin–aldosterone system (RAAS), insulin resistance, obesity, catecholamines, oxidative stress, inflammatory mediators, and high fructose and salt intake are all MetS-related factors that lead to the development of hypertension." (PMID 40565979, 2025). "In patients with hypertension and not prescribed antihypertensives, Hispanic patients had higher plasma renin activity (PRA) compared to White and Black patients." (PMID 40868074, 2025). "Subclinical PA is a biochemical phenotype characterized by renin-independent, andrelatively non-suppressible, aldosterone production that originates in normotensivepeople and precedes the development of hypertension." (PMID 41312955, 2025). "Globally prevalent conditions such as hypertension, heart failure, ischaemic heart disease (IHD) and chronic kidney disease (CKD) are frequently and effectively treated with blockers of the renin-angiotensin-aldosterone system (RAAS) as a first line treatment in the UK and worldwide." (PMID 40044928, 2025). "This is further evidenced by higher serum concentrations of alternative Ang metabolites and renin in aneurysm patients without recorded arterial hypertension (and therefore no pharmaceutical interference in the RAS)." (PMID 40003968, 2025).
Hypertension (continued). "Despite the effects of many antihypertensive agents on the renin–angiotensin–aldosterone system, ongoing efforts to manage hypertension should not be discontinued solely for the purposes of screening." (PMID 40113595, 2025). "In Cuba, half of adults who tested positive for uACR also had uncontrolled hypertension but were not receiving renin–angiotensin system blockers." (PMID 41345917, 2025). "This relative hypertension, combined with low prorenin levels due to the absent CL, appears to suppress the renin–angiotensin-aldosterone system (RAAS)." (PMID 40972010, 2025). "By activating the renin-angiotensin system and generating ROS in the paraventricular nucleus, direct inhibition of IL-1β, the primary proinflammatory cytokine in the NLRP3 inflammasome pathway, in addition to blocking NF-κB, also reduces hypertension." (PMID 40079000, 2025). "Animal models lacking vitamin - D receptors exhibit both arterial hypertension and increased renin expression." (PMID 40822817, 2025). "The father of Patient 4 had no glucose disorders, but arterial hypertension since youth with normal aldosterone/renin ratio." (PMID 41561050, 2025). "Subclinical PA refers to the identification ofbiochemical renin-independent aldosterone production in individuals with normalblood pressure and those with mild hypertension without signs or symptoms of overtPA." (PMID 41312955, 2025). "The renin–angiotensin system (RAS) is well known to be involved in sodium handling and in modulating neural autonomic cardiovascular regulation, two key factors influencing nocturnal hypertension." (PMID 40509714, 2025). "Once secreted, angiotensinogen undergoes enzymatic cleavage by renin, which is primarily produced by the kidneys in response to RAS activation, into angiotensin I (Ang I), with any disruption in this balance contributing to hypertension." (PMID 40969606, 2025). "The ACE I/D and AGTR1 A/C gene polymorphisms, as part of the renin–angiotensin system (RAS), have been associated with the risk of hypertension, diabetes, CVD, and nondiabetic renal disease." (PMID 40149592, 2025). "While study of the renin-angiotensin system (RAS) began with Robert Tigerstedt’s 1898 identification of renin in the kidney, it was Harry Goldblatt’s 1934 finding that hypertension was induced by clamping the renal artery which triggered a burst of biochemical research in the field." (PMID 38763333, 2024). "Renin-angiotensin system (RAS) inhibitors, which can prevent hypertension and CKD progression, might have obscured the synergistic effect between BP and glucose status on the CKD risk." (PMID 38671217, 2024). "Approximately 1 in 4 people with hypertension have low renin, but most do not meet thecriteria for primary aldosteronism or have a monogenetic cause." (PMID 39281005, 2024). "Renin-angiotensin-aldosterone system (RAAS) inhibitors, including angiotensin-converting enzyme inhibitors (ACEIs) and angiotensin receptor blockers (ARBs), are commonly used in the management of hypertension." (PMID 38496070, 2024). "Therefore, simultaneous inhibition of renin and ACE is an effective therapy for controlling hypertension." (PMID 39796531, 2024). "Activation of the classical renin–angiotensin system (RAS) pathway—specifically, the angiotensin-converting enzyme (ACE)-angiotensin II (Ang II)-angiotensin type 1 receptor (AT1R) axis—promotes the development of hypertension." (PMID 39339768, 2024). "It should be noted that hypertension and hypokalemia are not fundamental manifestations of PA, but, rather, depend on the severity and duration of exposure to renin–autonomous-aldosterone secretion and sodium retention." (PMID 39595045, 2024). "There are several metabolic processes that can influence the development of hypertension, notably, the renin–angiotensin–aldosterone system, if not properly regulated." (PMID 38256745, 2024).
Hypertension (continued). "In patients with hypertension but without a PA diagnosis, those with suppressed renin levels experience a greater blood pressure reduction from MRA treatment, particularly if they have higher plasma aldosterone levels within the normal range." (PMID 39877848, 2024). "Previous studies have demonstrated that the renin-angiotensin system (RAS)-mediated hypertension is abolished in rats lacking a functional gene for IL-1β." (PMID 39171117, 2024). "Left ventricular hypertrophy and hypertension result from the activation of androgen receptors in the heart and skeletal muscle with AAS, leading to the renin-angiotensin-aldosterone system (RAAS) stimulation, which has been linked to sudden cardiac death and worsening of heart failure." (PMID 39280364, 2024). "The same group reported that a lack of renin in principal cells of the collecting duct attenuated Ang II-induced hypertension." (PMID 39273497, 2024). "The primary purpose of this review is to examine renin–angiotensin–aldosterone system (RAAS) activity, transforming growth factor-β1 (TGF-β1), vascular calcification (VC), uremic toxins, and hypertension in the context of their impact on the occurrence and the course of CKD." (PMID 38727287, 2024). "Case Presentation: A 38-year-old male with diabetes, dyslipidemia, and hypertension was treated with early and comprehensive OMT, including statins, ezetimibe, sodium-glucose cotransporter 2 inhibitors (SGLT2i), pioglitazone, and renin-angiotensin system inhibitors." (PMID 39589971, 2024). "A disproportionate activation of the renin–angiotensin–aldosterone system has been also found to contribute to the development of hypertension in both non-diabetic and diabetic CKD." (PMID 38424466, 2024). "Reduction in the expression of renin, AGT, ACE1, and AT1R following STS-loaded NP therapy may help mitigate the detrimental effects of CKD-induced hypertension." (PMID 39765901, 2024). "Furthermore, studies have reported that a high-salt diet directly activates the renin-angiotensin-aldosterone system (RAAS), which is an additional mechanism contributing to the development of high blood pressure." (PMID 38420263, 2024). "Consequently, there is an accumulation of salts in the body, triggering an excessive activation of the sympathetic nervous system and renin-angiotensin-aldosterone system (RAAS), ultimately leading to hypertension." (PMID 37659996, 2023). "Although hypertension is a multifactorial medical disorder, the renin-angiotensin-aldosterone system (RAAS) is recognized as one of the most important regulators of basal blood pressure homeostasis and a major contributor in the development of hypertension." (PMID 37404743, 2023). "Among the 22 patients without PA (control group), 6 patients had low-renin hypertension with suppressed DRC (<4 μU/mL) and low aldosterone levels (<7 ng/dL; 194 pmol/L)." (PMID 38075562, 2023). "The renin-angiotensin-aldosterone system (RAAS) is the main regulatory system of hemodynamics in humans, and impairments in RAAS strongly affect the development and maintenance of arterial hypertension." (PMID 37848834, 2023). "KEGG analysis also detected alterations in pathways associated with many of the co-morbidities known as risk factors for increased COVID-19 severity, such as diabetes (AGE-RAGE signaling; albeit not significant) and hypertension (renin-angiotensin system)." (PMID 37015925, 2023). "The mechanism of RC-induced hypertension is not fully clarified, potentially involving vascular damage, oxidative stress, inflammation, insulin resistance and the renin-angiotensin system, while the role of hypertension in stroke has been well recognized." (PMID 37304024, 2023). "Liddle syndrome is an autosomal dominant hereditary disease characterized by early onset, uncontrolled hypertension, hypokalemia, low aldosterone, and renin activity levels, with or without metabolic alkalosis." (PMID 38013303, 2023).
Hypertension (continued). "Furthermore, renin, a key enzyme in the RAAS known to contribute to hypertension and CKD, was lower in αMUPA females and remained unaffected by AKI in this subgroup." (PMID 37887341, 2023). "In patients with hypertension, due to factors such as arterial remodelling and renin-angiotensin system, the CA curve is shifted to the right and cerebral ischemia can occur at higher MAPs compared to patients without hypertension." (PMID 37351255, 2023). "Renin–angiotensin–aldosterone system (RAAS) blockade, achieved through use of ACE inhibitors and angiotensin-II receptor blockers (ARBs), can reduce systolic BP, comparable to that achieved by calcium-channel blockers (CCBs) in HD patients with hypertension." (PMID 37672130, 2023). "Second, insulin resistance may stimulate the renin-angiotensin-aldosterone system (RAAS), produce the reabsorption of H2O and Na+, and increase vascular activity, eventually leading to hypertension." (PMID 37759253, 2023). "We have previously shown that an excess of deoxycorticosterone acetate and high sodium chloride intake (DOCA/salt) in one-renin gene mice induces a high urinary Na/K ratio, hypokalemia, and cardiac and renal hypertrophy in the absence of hypertension." (PMID 38069178, 2023). "Several theories have been postulated to explain the disparity, but the predominant explanations among these are the effects of renin-angiotensin system (RAS), testosterone, and sex hormones that disproportionately increase the odds of hypertension among males." (PMID 37908015, 2023). "Since most of patients with PA had severe hypertension, it is not possible in clinical practice to change all medications that can affect aldosterone/renin profile." (PMID 38075562, 2023). "In clinical practice, however, PA is often overlooked due to lack of measurement of plasma renin activity and aldosterone levels in subjects with hypertension." (PMID 37591913, 2023). "Dapagliflozin effectively reduces albuminuria after renin-angiotensin system blockade therapy in patients with T2DM and hypertension, improves glycemic control, reduces systolic blood pressure, and promotes uric acid excretion, thus reducing renal and cardiovascular risks." (PMID 37280615, 2023). "Monocyte/macrophage express ATR, angiotensinogen, renin, as well as angiotensin peptide hormone thus, monocyte/macrophage activity and function is modulated by RAS components during hypertension." (PMID 37854465, 2023). "Forth, previous studies found that remission of hypertension or T2DM might be related to hormones, including renin, angiotensin, aldosterone, ghrelin, glucagon-like peptide (GLP)-1 and GLP-23,14,30,31." (PMID 37914834, 2023). "Renin and aldosterone are important in those who present with potassium abnormalities (hypo/hyperkalaemia) with or without hypertension." (PMID 35585366, 2023). "Many hypertension patients have traditionally had low levels of renin and angiotensin II, and medicines that block the renin–angiotensin system have not been particularly successful." (PMID 37887299, 2023). "The treatment with EESM (at its highest dose) prevented ET1-induced hypertension without affecting the renin-angiotensin system, suggesting the direct role of the endothelin signalling pathway." (PMID 38161789, 2023). "Such a combination is not recommended by any current hypertension guidelines, because β‐blockers suppress renin secretion and reduce the plasma levels of angiotensin II and, therefore, perceived to be less additive in antihypertensive efficacy to ACEIs/ARBs." (PMID 36756690, 2023). "Unlike normotension, the renin-angiotensin-aldosterone system is overactivated in hypertension, which leads to an increase of systemic production of AngII." (PMID 36046692, 2022). "Considering the renin/PRR axis and Ang II/AT1R axis both promote hypertension, it is possible that d-cysteine could influence the RAS towards its BP-lowering benefit." (PMID 35326133, 2022).
Hypertension (continued). "The generation of renin results in the increased production of angiotensin I and ACE-1 is responsible for the conversion of angiotensin I to the potent vasoconstrictor angiotensin II, which results in elevated blood pressure and hypertension activity." (PMID 35206049, 2022). "Possible mechanisms could be related to the following aspects: First, IR can stimulate the activity of the renin-angiotensin-aldosterone system (RAAS), which further promotes salt absorption and water–sodium retention, and ultimately leads to hypertension." (PMID 36035963, 2022). "Although the pathophysiological mechanism of hypertension is not fully elucidated yet, a large number of pieces of evidence have shown that genetic alterations in the renin-angiotensin-aldosterone system play a central role." (PMID 36355860, 2022). "Previous reports indicated hypertension, diabetes, low baseline eGFR, cardiac disorders, high-dose SMX/TMP, concomitant use of renin-angiotensin system blockers, potassium-sparing diuretics, and potassium supplements are risk factors for AKI associated with SMX/TMP." (PMID 35909129, 2022). "The Kyoto Encyclopedia of Genes and Genomes (KEGG) enrichment analysis of key targets revealed that the relevant molecular action pathways of GJD in the treatment of hypertension include the Toll-like receptor, MAPK, PI3K-Akt, and renin-angiotensin signaling pathways." (PMID 36046450, 2022). "Renin–angiotensin–aldosterone System: The renin–angiotensin–aldosterone system previously has been studied as a potential marker in CSVD because it works in the regulation of vascular smooth muscle constriction and hypertension." (PMID 36119691, 2022). "These factors may promote sex steroid receptor-mediated alterations to the Renin–Angiotensin–Aldosterone System (RAAS), and increases in oxidative stress and inflammation, thereby contributing to the development of hypertension and vascular injury with age." (PMID 34230581, 2022). "Since hypertension will normally suppress renin release, it is not unlikely that low systemic RAS activity indeed occurs in combination with high renal RAS activity (due to enhanced AGT uptake)." (PMID 35710133, 2022). "In summary, these reports have shown that phenolics may regulate RAS by inhibiting renin and/or ACE and have a beneficial effect on the treatment of hypertension." (PMID 35424726, 2022). "Blacks are two times more likely than whites to have a low-renin form of hypertension, with high levels of aldosterone that are not proportionate with renin levels." (PMID 35701852, 2022). "Three patients were currently on renin-angiotensin system inhibitor treatment for hypertension, and 5 of them received non-steroidal anti-inflammatory drugs." (PMID 36133577, 2022). "Of note, no proteinuria and hypertension (and no renin–angiotensin–aldosterone system inhibition) were reported in the DDD patient with an eGFR of 89 ml/min/1.73 m2." (PMID 34476601, 2022). "Aliskiren, the only currently available direct renin inhibitor, is approved for the treatment of hypertension but has not been widely adopted outside niche contexts." (PMID 35620081, 2022). "The renin-angiotensin-aldosterone system (RAAS) is a hormonal system that plays a fundamental role in blood pressure regulation by controlling vasoconstriction and sodium and fluid homeostasis, and it is an important mediator of essential hypertension." (PMID 36364047, 2022). "In conclusion, PAN treatment induced upregulated renin secretion, which subsequently increased ANGII and AGTR1 expression and which may lead to the emergence of pathological conditions such as high blood pressure under certain circumstances." (PMID 35203286, 2022). "The deficiency of vitamin D, as a negative endocrine regulator of renin biosynthesis, leads to elevated renin and angiotensin II production, consequently leading to high blood pressure (BP) and cardiac hypertrophy." (PMID 35581625, 2022).